MIRLET7I (microRNA let-7i)
Synonyms: hsa-let-7i; LET7I; MIRNLET7I; let-7i
Gene: MicroRNA gene on chromosome 12 (62,603,686 to 62,603,769, forward strand). Ensembl gene ENSG00000199179.
Gene Ontology:
Biological process: miRNA-mediated post-transcriptional gene silencing
Cellular component: RISC complex
Homologues: Orthologues: chimpanzee ptr-let-7i (100% identical), guinea pig MIRLET7I (100% identical), macaque mml-let-7i (100% identical), mouse Mirlet7i (100% identical), pig MIRLET7I (100% identical), rabbit MIRLET7I (100% identical), tropical clawed frog xtr-let-7i (99% identical), zebrafish dre-let-7i (92% identical), tropical clawed frog xtr-let-7b (77% identical), Drosophila melanogaster mir-let7 (44% identical). Paralogues in human: MIRLET7G (67% identical), MIRLET7D (62% identical), MIRLET7F1 (61% identical), MIR98 (58% identical), MIRLET7F2 (58% identical), MIRLET7A3 (57% identical), MIRLET7A1 (56% identical), MIRLET7C (54% identical), MIRLET7E (52% identical), MIRLET7A2 (51% identical).
Diseases named in the same sentence as MIRLET7I in open-access papers:
MIRLET7I is named in the same sentence as 1 disease in open-access papers, as found by Europe PMC text mining. Sharing a sentence is not in itself a finding about the gene and the disease.
MIRLET7I shares sentences with these, for which no sentence is quoted: ovarian carcinoma (1 paper).